REN (renin)
Diseases named in the same sentence as REN in open-access papers (continued):
Sharing a sentence is not in itself a finding about the gene and the disease.
kidney disease (continued). "Renin-angiotensin system inhibitors (RASIs) have been suggested as potential therapeutic agents for cardiovascular and renal diseases." (PMID 39289938, 2025). "Nevertheless, given that RAS plays a key role in the pathophysiology of kidney diseases, renin activation likely contributes to kidney injury following chronic PM2.5 exposure." (PMID 40699786, 2025). "One study found that a decrease in E2 synthesis in experimental animals following ovariectomy (OVX) accelerates renal disease progression by affecting the renin-angiotensin system’s activity." (PMID 39941126, 2025). "Our simulations echo the potential risk of CCB monotherapy in AA CKD patients and support blockade of the renin angiotensin system as a valuable tool in renal disease treatment when combined with CCB therapy." (PMID 39606582, 2024). "The proportion of patients on immunosuppression was lower in patients with monogenic kidney disorders in all 3 cohorts, as was renin-angiotensin blockade in both Columbia-GN and Columbia-CKD." (PMID 39225089, 2024). "In cases where diabetic patients have macroalbuminuria, microalbuminuria, or renal disease, the first line of treatment that should be used is inhibition of the renin–angiotensin–aldosterone system." (PMID 39407846, 2024). "By leveraging two populations of Ugandan children that differ based on age, the presence of pre-existing kidney disease, and underlying mechanisms of AKI, we were able to evaluate and validate renin as a biomarker of AKI and mortality in children." (PMID 37842390, 2023). "Other RAS inhibitors, such as angiotensin II receptor blockers (ARBs), renin inhibitors and even chymase inhibitors (CI), are now considered key drugs for the treatment of hypertensive patients with kidney disease." (PMID 38203500, 2023). "Kidney disease progression is accelerated by iron overload through the induction of inflammation and fibrosis via oxidative stress and activation of the renin-angiotensin system." (PMID 36650247, 2023). "Current treatment includes the use of renin-angiotensin-aldosterone system inhibitors which slow progression of kidney disease and prolong life expectancy." (PMID 35547199, 2022). "Thus, the manifestation of a kidney disease pattern in patients carrying the Sec61α–V67G or Sec61α–T185A mutation could very well be explained by the substrate-specific retention of REN and eventually UMOD in or at the ER, thereby hampering their efficient secretion." (PMID 35064074, 2022). "More reliable identification of kidney dysfunction would allow earlier intervention to delay progression of kidney disease such as targeting renin-angiotensin-aldosterone system and properly dosing medications to minimize nephrotoxin exposure." (PMID 36060680, 2022). "First proposed in the 2015 Kidney Disease: Improving Global Outcomes (KDIGO) consensus report, ADTKD is currently believed to be caused by gene mutations UMOD, REN, MUC1, HNF1B, SEC61A, and DNAJB11." (PMID 36362756, 2022). "Median prevalence of HK in patients with renal disease receiving HD was 21.6% and increased in patients receiving concomitant medications – mainly renin–angiotensin–aldosterone system inhibitors and potassium-sparing diuretics." (PMID 33478329, 2021). "Hypertension is a prevalent symptom in renal disorders, and it is considered to occur through defects in the renin-angiotensin-aldosterone system (RAAS), monogenic abnormalities of ion transporters and acute kidney inflammation." (PMID 36699147, 2021). "In general, women are protected against renal diseases compared with men through estrogen’s inhibition and androgen’s activation of the renin-angiotensin system." (PMID 34622098, 2021). "Risk factors for this dyselectrolytemia include female gender, chronic heart or kidney disease, medication with thiazides, blockers of the renin-angiotensin system or serotonin reuptake inhibitors and genetic factors." (PMID 31276475, 2019).
kidney disease (continued). "The physiological functions of soyasaponins are reported to be anti-oxidative with anti-kidney-disease progression, anti-inflammatory, and anti-tumor effects and to result in reduced blood glucose level, renin inhibition, and hepatoprotection." (PMID 30154422, 2018). "In conclusion, histological studies together with clinical and laboratory features are crucial for prognostic assessment and treatment planning of HIV-associated renal diseases, focused on early ART and inhibition of the renin-angiotensin system." (PMID 27007656, 2016). "One of the main proposed mechanisms linking vitamin D with renal-vascular and kidney disease is regulation of the renin-angiotensin system (RAS)." (PMID 23971740, 2013). "Ongoing studies are evaluating the role of renin inhibitors in the prevention of cardiovascular events and slowing of kidney disease progression in CKD." (PMID 27713228, 2009). "Succinate is an activator of the renin-angiotensin system, a pivotal mechanism in renal diseases." (PMID 41329536, 2025). "The disruption of the renin–angiotensin system can lead to kidney disease onset and progression." (PMID 40362266, 2025). "The renin-angiotensin-aldosterone system (RAAS) is a regulatory mechanism within the endocrine system, associated with various diseases, including HTN, cardiovascular, and renal diseases." (PMID 40386051, 2025). "Renin may mediate the inflammatory milieu in kidney disease and its contribution to the adverse cardiovascular outcomes noted in ESKD." (PMID 38040779, 2023). "The mechanism of the possible protective role that VitD may play in kidney disease is thought due to VitD’s suppression of the renin-angiotensin-aldosterone system (RAAS) leading to improved estimated glomerular filtration rate (eGFR)." (PMID 36386950, 2022). "The higher values of blood pressure might be related to more active kidney disease, stimulating hormonal disorders responsible for blood pressure control, including activation of the renin–angiotensin–aldosterone system." (PMID 34679462, 2021). "The present data show a robust induction of Ren1 expression in the vascular smooth muscle cells of the kidney after single and repeated GLP‐1R activation and this renin recruitment may be involved in the effects of GLP‐1R agonist treatment on kidney disease." (PMID 34277961, 2021). "Glomerular hyperfiltration, overactive renin-angiotensin-aldosterone system, and renal dynamic changes may all contribute to renal disease." (PMID 32572359, 2020). "Estrogen also stimulates both the renin–angiotensin system and angiotensinogen that may exert specific deleterious effect on progression of renal disease." (PMID 31585527, 2019). "Estrogen also activates both the renin-angiotensin system and angiotensinogen that may exert specific deleterious effect on progression of renal disease." (PMID 31585527, 2019). "Renin-angiotensin system inhibitors (RAS) drugs have a proteinuria-reducing effect that could prevent the progression of kidney disease in diabetic patients." (PMID 30817790, 2019). "In addition, drugs currently used as therapy for kidney disease, such as inhibitors of the renin-angiotensin system, directly or indirectly inhibit fibrosis." (PMID 30356276, 2018). "The renin-angiotensin system (RAS) has a significant influence on renal disease progression." (PMID 29157100, 2017). "This follows evidence and guidelines that renin-angiotensin system blockade may slow renal disease progression in XLAS males." (PMID 25739341, 2015). "Therefore, current pharmacotherapeutic strategies have focused on inhibiting the production of Ang II (ACE inhibitors and direct renin inhibitors) or AT1R blockade [angiotensin receptor blockers (ARBs)] to delay the progression of renal diseases." (PMID 26556707, 2015). "However, there are established overlaps, such as the RAS pathway which is involved in renal function decline since treatment of patients with renin-angiotensin inhibitors slows the progression of kidney disease." (PMID 24658007, 2014).
kidney disease (continued). "Adequate blood pressure control and reduction of urine protein excretion, preferably obtained by the use of renin-angiotensin-aldosterone system inhibitors, have traditionally been considered the mainstay of therapeutic strategies in patients with renal disease." (PMID 24092648, 2013). "Furthermore, progression of renal disease was observed despite normalization of plasma renin activity." (PMID 24025423, 2013). "The present study demonstrated that combination of chymase inhibitor chymostatin and renin inhibitor aliskiren markedly attenuated ER stress and apoptosis induced by lipid overload in cultured tubular cells, suggesting a role of intracellular RAS in lipid-associated kidney diseases." (PMID 30064425, 2018). "The angiotensin II type 1 (AT1) receptor is a key component of the renin-angiotensin system (RAS) and a validated target for cardiovascular and renal disorders." (PMID 42280273, 2026). "Renin-angiotensin-aldosterone system (RAAS) blockade has been a mainstay of therapy in cardiovascular and kidney disease for nearly 30 years." (PMID 42291564, 2026). "Angiotensin II, a key component of the renin–angiotensin–aldosterone system (RAAS), is known to play an important role in the pathophysiology of cardiovascular and renal diseases." (PMID 40109358, 2025). "Renin, GDF15, PRSS8, RARRES2, PGLYRP1, LOX1, and UPAR, all robustly related to PA, have been related to cardiovascular or kidney disease via different pathways." (PMID 40498722, 2025). "Angiotensin-converting enzyme 2 (ACE2) played an important role in the renin-angiotensin-aldosterone system (RAAS) and it was proved to be renoprotective in renal disease." (PMID 38756510, 2024). "The renin–angiotensin–aldosterone system (RAAS) activation can be compensatory in the early stages of cardiovascular and renal diseases, but its long-term activation is maladaptive." (PMID 35049831, 2022). "Later, the host renin–angiotensin–aldosterone system (RAAS) is activated, leading to tissue damage characterized by cardiovascular and renal disease." (PMID 36499094, 2022). "Previous studies suggested that renal disorder results in ventricular dysfunction and deteriorates remodeling after AMI through excessive renin-angiotensin activation." (PMID 34220312, 2021). "Angiotensin II (Ang II), the main effector peptide of the renin-angiotensin system (RAS), plays a central role in the pathophysiology of renal diseases." (PMID 28270699, 2017). "Evidence for the potential role of organ specific cardiovascular renin–angiotensin systems (RAS) has been demonstrated experimentally and clinically with respect to certain cardiovascular and renal diseases." (PMID 24600438, 2014). "AGT plays a role in the renin-angiotensin system (RAS), a primary pathway in blood pressure regulation with strong influences on cardiovascular and renal disease." (PMID 24658007, 2014). "Blockade of the renin-angiotensin system (RAS) is well recognized as an essential therapy in hypertensive, heart, and kidney diseases." (PMID 22126210, 2011). "Two pivotal phase III trials, FIDELIO-DKD and FIGARO-DKD, demonstrated that finerenone, when added to the maximum tolerated dose of a renin–angiotensin–aldosterone system (RAAS) inhibitor, significantly reduced proteinuria, cardiovascular events, and renal disease progression." (PMID 41296390, 2025). "Renal local renin–angiotensin system–activation plays an essential role in DN progression, and the dysregulation of ACE2 expression is closely related to the incidence and development of kidney disease." (PMID 39444490, 2024). "Thus, in contrast to spironolactone and eplerenone, finerenone has demonstrated to slow the progression of kidney disease and also prevent CV complications in persons with CKD and T2D on top of renin-angiotensin system inhibition." (PMID 36719097, 2023).
kidney disease (continued). "The three remaining RAAS genes included in this meta-analysis, ACE2, AGTR2 and REN, have not been researched as extensively as ACE, AGT and AGTR1 for associations with renal disease." (PMID 31048445, 2019). "The renin-angiotensin-aldosterone system (RAAS) is an endocrine cascade that is a current target in the treatment of hypertension and prevention of cardiovascular or kidney disease." (PMID 26556707, 2015). "Timely blockade with ACE inhibitors, renin inhibitors or AT1 receptor antagonists can promote reversal of renal lesions and ultimately prevent the evolution towards end-stage organ failure in experimental models of renal disease." (PMID 22403621, 2012). "Activation of the renin-angiotensin-aldosterone system (RAAS) is pivotal to the pathogenesis of much renal disease, and accounts in part for the close relationship between renal disease and cardiovascular complications." (PMID 23259697, 2012). "Thus, in Dahl SS rats, administration of sacubitril without renin-angiotensin-system blockage had adverse effects on renal disease progression, particularly in regards to glomerular damage and protein cast formation." (PMID 33541194, 2021).
cancer (166 papers, 2004 to 2026). A tumor composed of atypical neoplastic, often pleomorphic cells that invade other tissues. "Cancer-associated fibroblasts express components of the renin–angiotensin system, including AT1R, which upon activation leads to TGF-β formation, stimulating EMT and promoting metastasis and treatment resistance." (PMID 39941158, 2025). "Alternatively, previous studies using mouse models and cancer cell lines have directly implicated the renin-angiotensin system in the regulation of cell proliferation, angiogenesis, tumor expansion, as well as metastasis." (PMID 35235571, 2022). "The functions of OSBPL family members were mainly associated with several potential signaling pathways in cancer cells, including ATP binding, integrin binding, receptor binding, and the renin-angiotensin system (RAS) signaling pathway." (PMID 34829830, 2021). "Local recurrence is inevitable due to the quiescent cancer stem cells (CSCs) in GB that co-express stemness-associated markers and components of the renin–angiotensin system (RAS)." (PMID 34439159, 2021). "Angiotensin (Ang) II, the main effector peptide of the renin-angiotensin system, has been implicated in multiple aspects of cancer progression such as proliferation, migration, invasion, angiogenesis and metastasis." (PMID 29179450, 2017). "Together with the progressive loss overall of both (pro)renin mRNA and protein, such physical disruption suggests that the system for local Ang II generation is greatly impaired in cancer." (PMID 16755291, 2006). "In cancer, overall renin transcription was seemingly reduced with the loss of myoepithelial cells, and it also became more sporadic in fibroblasts." (PMID 16755291, 2006). "However, functions of ACE and the renin-angiotensin system have also been linked to cancer, tumor microenvironment, and (cancer) immunity." (PMID 40235590, 2025). "The enzyme renin encoded by this gene, has a role in the renin-angiotensin system; this system regulates angiogenesis and may have a role in cancer development and progression." (PMID 35659616, 2022). "Renin–angiotensin system components have been implicated in cancer development." (PMID 31484460, 2019). "Besides, there is increasing evidence that the renin-angiotensin system pathway may drive malignant tumor progression through inhibition of apoptosis associated with enhanced tumor proliferation, cell migration, tissue invasion, and angiogenesis." (PMID 37370793, 2023). "The renin-angiotensin system (RAS) plays a central role in regulating blood pressure and has recently been implicated in cancer biology." (PMID 41549123, 2026). "Components of the renin–angiotensin system are expressed locally in many tumors by cancer cells, immune cells, and stromal cells." (PMID 39941158, 2025). "Together, these signaling pathways within the TME demonstrate the complex interplay between the renin–angiotensin system and the various cellular components that contribute to cancer progression and the possible maintenance of the CSC phenotype." (PMID 39941158, 2025). "The combination of renin-angiotensin system inhibitors with cyclin-dependent kinase 4/6 inhibitors is an emerging area of interest in cancer research." (PMID 41417371, 2025). "The renin–angiotensin system (RAS) has been increasingly recognized to be associated with carcinogenesis and cancer progression." (PMID 40974486, 2025). "Inhibitors of the renin-angiotensin system are frequently prescribed for antihypertension therapy and can affect cancer aggressiveness by inhibiting collagen synthesis in several different cancers." (PMID 39430410, 2024). "In fact, the renin-angiotensin system has been found to be highly expressed in tumors from different types of cancers." (PMID 37371679, 2023). "TMEM158 plays an important role in many cancers since it is upregulated in the renin-angiotensin system (Ras)-induced senescence process." (PMID 37064154, 2023).